MFAP3 (microfibril associated protein 3)
Description:
Component of the elastin-associated microfibrils.
Tractability: Antibody: UniProt places it where antibodies can reach, with high confidence; its Gene Ontology location is reachable by antibodies, with high confidence; UniProt predicts a signal peptide or a membrane-spanning region. PROTAC: ubiquitination databases record sites on it.
Gene: Protein-coding gene on chromosome 5 (154,038,959 to 154,220,478, forward strand). Ensembl gene ENSG00000037749.
Subcellular location: Cell membrane
Subcellular location (Human Protein Atlas): Golgi apparatus; Nucleoplasm
Pathways (Reactome):
Extracellular matrix organization: Molecules associated with elastic fibres
Gene Ontology:
Molecular function: protein binding
Cellular component: extracellular region; microfibril; non-collagenous component of interstitial matrix; plasma membrane
Genetic constraint (gnomAD): Loss-of-function variants: 9 observed, 23.88 expected, observed/expected ratio (o/e) 0.38, 90% interval 0.23 to 0.66. The upper end of that interval is the gene's LOEUF score, 0.66, which puts it in group 2 of 6, group 1 being the genes least tolerant of losing a copy. Missense variants: 398 observed, 466.33 expected, observed/expected ratio (o/e) 0.85, 90% interval 0.79 to 0.93. Synonymous variants: 140 observed, 163.6 expected, observed/expected ratio (o/e) 0.86, 90% interval 0.75 to 0.99.
Homologues: Orthologues: chimpanzee MFAP3 (99% identical), macaque MFAP3 (99% identical), rabbit MFAP3 (90% identical), dog MFAP3 (89% identical), pig MFAP3 (88% identical), guinea pig MFAP3 (81% identical), rat Mfap3 (81% identical), mouse Mfap3 (81% identical), tropical clawed frog mfap3 (56% identical). Paralogues in human: MFAP3L (49% identical).
Diseases named in the same sentence as MFAP3 in open-access papers:
MFAP3 is named in the same sentence as 3 diseases in open-access papers, as found by Europe PMC text mining. Sharing a sentence is not in itself a finding about the gene and the disease. The quoted sentences say what the papers report.
cancer (1 paper, 2025). A tumor composed of atypical neoplastic, often pleomorphic cells that invade other tissues. "MFAP1, MFAP2 and MFAP3 were up-regulated in both EAC and ESCC, while MFAP4 and MFAP5 were down-regulated in cancer tissues, indicating that MFAP2 might play crucial role in ESCC." (PMID 40657371, 2025).
MFAP3 also shares sentences with these, for which no sentence is quoted: arteriosclerosis (1 paper); esophageal cancer (1).